IGFBP3 (insulin like growth factor binding protein 3)
Diseases named in the same sentence as IGFBP3 in open-access papers (continued):
Sharing a sentence is not in itself a finding about the gene and the disease.
Parkinson disease (2 papers, 2009 to 2015). A progressive degenerative disorder of the central nervous system characterized by loss of dopamine producing neurons in the substantia nigra and the presence of Lewy bodies in the substantia nigra and locus coeruleus. "The aim of this study was to investigate the role of circulating growth hormone (GH), insulin growth factor-1 (IGF-1), IGF binding protein-3 (IGFBP-3), and nitric oxide (NO) concentrations in the patients suffering from Parkinson's disease (PD)." (PMID 19300521, 2009).
pituitary tumor (2 papers, 2018 to 2024). A benign or malignant neoplasm affecting the pituitary gland. "This is the first study to focus on the effects of the IGFBP3 polymorphism on pituitary tumor characteristics and surgical outcome in Chinese acromegalic patients." (PMID 30619084, 2018).
postmenopausal osteoporosis (2 papers, 2018 to 2023). Metabolic disorder associated with fractures of the femoral neck, vertebrae, and distal forearm. "The ROC curve determined diagnostic values of circulating IGFBP-3 and IL-6 levels for postmenopausal osteoporosis." (PMID 37035758, 2023). "In addition, the potential diagnostic role of circulating IGFBP-3 and IL-6 in the pathogenesis of postmenopausal osteoporosis in postmenopausal women was investigated." (PMID 37035758, 2023). "An analysis of ROC curves showed that circulating levels of IGFBP-3 and IL-6 could be identified as reliable diagnostic biomarkers for postmenopausal osteoporosis." (PMID 37035758, 2023). "The potential role of IGFBP-3 and IL-6 in the diagnosis of postmenopausal osteoporosis was predicted using the area under the receiver operating characteristic curve (ROC, AUC)." (PMID 37035758, 2023). "Although these data suggest an inhibitory role for IGFBP-3 in bone metabolism, other in vivo data and cross-sectional studies in a cohort of female patients with postmenopausal osteoporosis suggest an anabolic role for IGFBP-3 in maintaining bone density." (PMID 29503631, 2018). "Circulating IGFBP-3 and IL-6 might be essential predictors of postmenopausal osteoporosis and can help predict osteoporotic fracture." (PMID 37035758, 2023). "Circulating measurements of IGFBP-3 and IL-6 might be essential predictors of postmenopausal osteoporosis and could predict osteoporotic fracture." (PMID 37035758, 2023).
renal failure (2 papers, 2022 to 2024). "A low IGF binding protein 3 (IGFBP3), such as in renal failure, may on the other hand cause a falsely normal or low IGF-2/IGF-1 ratio." (PMID 38432069, 2024). "A low IGF binding protein 3 (IGFBP3), such as in renal failure, may also result in a falsely normal or low IGF-2/IGF-1 ratio." (PMID 38432069, 2024).
Rett syndrome (2 papers, 2021 to 2025). A severe neurodevelopmental disorder affecting the central nervous system. "One of the known neuropathologies that was linked to IGFBP3 malfunction is Rett syndrome." (PMID 33673334, 2021). "This may confirm the role of IGFBP3 overexpression in Rett syndrome pathogenesis." (PMID 33673334, 2021). "As IGFBP3 binds IGF-1 and IGF-1 mimetics have shown therapeutic benefits in Rett syndrome, targeting the IGF system may be a potential strategy for Rett syndrome (see Section 5.4)." (PMID 40943197, 2025).
schizophrenia (2 papers, 2020 to 2022). A major psychotic disorder characterized by abnormalities in the perception or expression of reality. "However, whether a change of IGF-2, IGFBP-3 and IGFBP-7 in patients is caused by schizophrenia itself or other confounding factors, for example, influenced by antipsychotic drugs, is still unknown." (PMID 32191705, 2020). "Further metabolic dysregulation was detected as an upregulation in IGFBP6 in schizophrenia and a decrease in IGF2 and IGFBP3/5/7/ALS." (PMID 34741130, 2022). "The schizophrenia patients had a much lower content of serum IGF-2, IGFBP-3 and IGFBP-7 than controls." (PMID 32191705, 2020). "Our paper indicates that there were much lower levels of serum IGF-2, IGFBP-3 and IGFBP-7 in Chinese schizophrenia patients." (PMID 32191705, 2020). "However, in contrast to our findings, one previous study performed in male Arab subjects demonstrated that serum IGF-2 content was much higher in schizophrenia patients, and no change was found in IGFBP-3 levels." (PMID 32191705, 2020).
thyroid nodule (2 papers, 2017 to 2024). A small circumscribed mass in the THYROID GLAND that can be of neoplastic growth or non-neoplastic abnormality. "It needs more studies with more subjects to evaluate the effects of IGF-1/IGFBP-3 levels on thyroid nodules and the risk of thyroid malignancy." (PMID 29081797, 2017). "In contrast, the AUC for the combined model incorporating IGF-1, IGFBP-3, and the IGF-1/IGFBP-3 molar ratio demonstrated a significant association with the presence of thyroid nodules in T2DM patients (AUC = 0.619, P < 0.001)." (PMID 39444449, 2024). "This study demonstrated the possible role of both IGF-1 and IGFBP-3 in the growth and the formation of multinodularity of thyroid nodules." (PMID 29081797, 2017). "According to our results, we suggested that a higher IGF-1 level in multinodular cases as well as an increase in IGFBP-3 level that was parallel to an increase in thyroid nodule size were the findings suggesting the role of IGF-1 and IGFBP-3 in the pathogenesis of nodular goiter." (PMID 29081797, 2017). "The results indicated that IGF-1, IGFBP-3, and the IGF-1/IGFBP-3 ratio individually exhibited an uncertain predictive value for thyroid nodules in patients with T2DM (AUC=0.527, AUC=0.501, AUC=0.504, P>0.05)." (PMID 39444449, 2024). "The ROC curve analysis evaluated the potential of serum IGF-1, IGFBP-3, and the IGF-1/IGFBP-3 molar ratio as predictors of thyroid nodules in patients with T2DM." (PMID 39444449, 2024). "With current guidelines generally advising against routine ultrasound screening for thyroid nodules in the general population, a combined predictive approach using IGF-1, IGFBP-3, and the IGF-1/IGFBP-3 ratio might hold promise for preventing thyroid nodules in T2DM patients." (PMID 39444449, 2024).
Turner syndrome (2 papers, 2014 to 2021). Turner syndrome is a chromosomal disorder associated with the complete or partial absence of an X chromosome. "Especially, the A allele in the IGFBP-3 promoter region reportedly causes an increase in IGFBP-3 expression, which reflects the growth rate in rhGH therapy in prepubertal children with GHD and Turner syndrome, but not ISS." (PMID 34723984, 2021). "Earlier studies have also suggested that the serum levels of insulin-like growth factor (IGF), insulin-like growth factor binding protein-3 (IGFBP3), anti-Müllerian hormone (AMH) and androgens are altered in individuals with Turner syndrome as compared to normal females." (PMID 24932682, 2014).
adrenocortical tumors (1 paper, 2014). "Additionally, the amplification of the IGFBP3, FGFR4 (data not shown), and NSD1 (data not shown) genes was also detected in this carcinoma, but IGF1R amplification was not demonstrated in the remaining cases with adrenocortical tumors." (PMID 25110710, 2014).
age (1 paper, 2022). A temporal measurement of the time period elapsed since an identifiable point in the life cycle of an organism. "IGFBP3 was upregulated in the CC with aging, suggesting that it may be a senescence-associated gene involved in age-related ED." (PMID 35154570, 2022).
alcoholic liver diseases (1 paper, 2025). A disorder caused by damage to the liver parenchyma due to alcohol consumption. "Other studies reveal increased IGFBP3 concentrations in postmenopausal women following daily alcohol consumption as well as increased IGFBP3 levels in both serum and liver tissue from patients with alcoholic liver disease." (PMID 39880903, 2025).
amenorrhea (1 paper, 2013). The absence of menses in a woman who has achieved reproductive age. "FN BMD was associated (P < 0.05 for all comparisons) with age at the time of evaluation, duration of anorexia nervosa, total duration of amenorrhea, sIGF-I, and IGFBP-3." (PMID 23634145, 2013).
anterior uveitis (1 paper, 2014). Inflammation of the iris and anterior chamber of the eye. "Similarly, we did not observe any difference in IGF-1 or IGFBP-3 levels when patients were stratified according to history of anterior uveitis, presence of syndesmophytes, hip involvement or synovitis in other peripheral joints, peripheral enthesitis, and HLA-B27 status (data not shown)." (PMID 25295265, 2014).
anxiety disorder (1 paper, 2021). A category of psychiatric disorders which are characterized by anxious feelings or fear often accompanied by physical symptoms associated with anxiety. "Plasma concentrations of total IGFBP-3 were significantly higher in patients with anxiety disorder than in patients without anxiety disorder (t54 = − 2.305, p = 0.025)." (PMID 34341419, 2021).
Aortic dissection (1 paper, 2025). Aortic dissection refers to a tear in the intimal layer of the aorta causing a separation between the intima and the medial layers of the aorta. "IGFBP-3 is downregulated in aortic tissues from patients with aortic dissection, and this is mediated by IGFBP-3 preserving aortic smooth muscle cells’ contractility and by reducing MMP9 activation." (PMID 41226289, 2025).
atopic dermatitis (1 paper, 2024). "In the logistic regression model, decreased levels of serum estradiol, dehydroepiandrosterone sulfate, FT4, and IGF-1, and increased levels of IGFBP3 were associated with an increased likelihood of exhibiting atopic dermatitis." (PMID 38812645, 2024).
atrial fibrillation (1 paper, 2023). A disorder characterized by an electrocardiographic finding of a supraventricular arrhythmia characterized by the replacement of consistent P waves by rapid oscillations or fibrillatory waves that vary in size, shape and timing and are accompanied by an irregular ventricular response. "Five feature m6A regulatory genes, ZC3H13, YTHDF1, HNRNPA2B1, IGFBP2, and IGFBP3, were determined (p < 0.05) to establish a nomogram model that can predict the incidence of atrial fibrillation with the RF model." (PMID 37435047, 2023).
Autoimmunity (1 paper, 2022). The occurrence of an immune reaction against the organism's own cells or tissues. "In particular, higher IGFBP3 plasma levels were found in 4-weeks and 10-week-old NOD mice, which are not hyperglycemic yet and in which beta cells are still detectable but already exhibit insulitis and islet-autoimmunity." (PMID 35115561, 2022).
bacteremia (1 paper, 2025). "Notably, all patients with bacteremia due to Enterococci from the gastrointestinal tract (n = 2 [100%]) were part of the low IGFBP-3 phenotype." (PMID 40724799, 2025).
benign breast tumor (1 paper, 2007). "The elevated expression of IGFBP3 in proliferative benign breast tumor is unexpected." (PMID 17210081, 2007).
bone cancer (1 paper, 2022). A primary or metastatic malignant neoplasm affecting the bone or articular cartilage. "The association of IGF-1, IGFBP-1, IGFBP-3 and IGF-1R with bone cancer different features." (PMID 36713521, 2022).
bone metastasis (1 paper, 2022). Transfer of a neoplasm from its primary site to bones. "The levels of MIP-1δ, MCP-2, TIMP-1, RANTES, IGFBP3, and TNF-α showed significant differences in the pairwise comparative analysis and may therefore mediate pain associated with bone metastasis." (PMID 35845981, 2022). "In addition, MIP-1δ, MCP-2, TIMP-1, RANTES, IGFBP3, and TNF-α expression levels were significantly different between the preradiotherapy and postradiotherapy groups and may thus be closely associated with bone metastasis-related pain." (PMID 35845981, 2022).
cataract (1 paper, 2025). Partial or complete opacity of the crystalline lens of one or both eyes that decreases visual acuity and eventually results in blindness. "Our findings indicated that the concentration of IGFBP3 was significantly elevated in aqueous humor of diabetic cataract patients compared to age-related cataract patients and control group, underscoring a potential biomarker for this ocular condition." (PMID 40620905, 2025).
Cerebral cavernous malformation 2 (1 paper, 2010). "Cerebral cavernous malformation 2 (CCM2), insulin-like growth factor binding protein 3 (IGFBP3), sarcospan (Kras oncogene-associated gene); (SSPN), and transforming growth factor, beta 2 (TGFB2) were selected and screened as candidates under these criteria." (PMID 21179236, 2010).
cerebral small vessel disease (1 paper, 2021). Cerebral small vessel disease is the term currently used to pathological processes that affect the brain parenchymal circulation (arterioles, capillaries, and veins). "Several studies have implied the possibility of a beneficial association between IGFBP-3 and cerebral small vessel disease." (PMID 33631000, 2021).
chordoma (1 paper, 2025). Chordomas are rare malignant tumors arising from embryonic remnants of the notochord in axial skeleton. "This indicated that IGFBP3 is secreted and glycosylated in chordoma cells, particularly evident after TBXT loss." (PMID 40901948, 2025). "IGFBP3 stood out for its extreme up-regulation after TBXT loss in several chordoma cell lines." (PMID 40901948, 2025). "Our initial data on IGFBP3 function in chordoma cells showed that it impairs spheroid growth and that its knockout partially reversed the growth-inhibitory effects of TBXT loss and modulated a subset of the TBXT-regulated proteome." (PMID 40901948, 2025). "We found that IGFBP3 is glycosylated and secreted in chordoma cells, especially when it is highly expressed after TBXT inhibition." (PMID 40901948, 2025). "In contrast, U-CH2 spheroids were unaffected, suggesting a cell line– and chordoma type–specific effect of IGFBP3." (PMID 40901948, 2025). "We next hypothesized that high IGFBP3 levels might be toxic to chordoma cells and, therefore, suppressed by TBXT and that the proliferation arrest caused by TBXT inhibition might be mediated by IGFBP3 reexpression." (PMID 40901948, 2025). "In summary, IGFBP3 may act as a regulator that fine-tunes specific transcriptional effects of TBXT in chordoma cells to create optimal growth conditions." (PMID 40901948, 2025). "However, our data also support a more direct regulatory relationship: TBXT may act as an upstream transcriptional regulator of IGFBP3 by binding to regulatory elements, potentially explaining its outlier expression in response to T-DARPin expression in chordoma cells." (PMID 40901948, 2025). "Together, we showed that part of the TBXT regulome is modulated by IGFBP3, particularly factors involved in the interferon response, suggesting that IGFBP3 can fine-tune the action of TBXT to precisely fulfill the requirements of chordoma cells for survival and proliferation." (PMID 40901948, 2025).
Chronic colitis (1 paper, 2025). A chronic inflammatory disease of the large intestine (colon, cecum and rectum). "Pharmacological blockade of IGFBP3/TMEM219 signal ameliorates DSS-mediated acute and chronic colitis in vivo." (PMID 40371646, 2025). "Genetic and pharmacological blockade of the IGFBP3/TMEM219 signaling successfully preserved ISCs and their self-renewal properties in vitro, enabled proliferation and recovery of intestinal crypts, and ameliorated the signs and symptoms of acute and chronic colitis in preclinical models in vivo." (PMID 40371646, 2025).
chronic hepatitis C (1 paper, 2022). "In comparison, IGFBP-3, an insulin growth factor transport protein, was downregulated in patients with chronic hepatitis C." (PMID 35659360, 2022).
Chronic viral hepatitis (1 paper, 2018). "Chronic viral hepatitis led to a reduction of IGF-1 and IGFBP-3 and increase in GH secretion." (PMID 29449867, 2018). "Chronic viral hepatitis leads to reduction of IGF-1 and IGFBP-3 and an increase in GH secretion." (PMID 29449867, 2018).
clubfoot (1 paper, 2025). The most common congenital deformation of the foot, occurring in 1 of 1,000 live births. "Specifically, common genetic variants near HOX homeobox genes, insulin-like growth factor binding protein 3 (IGFBP3, MIM 146732), and caspase genes have been reported to be associated with isolated clubfoot." (PMID 40746736, 2025).
cocaine addiction (1 paper, 2015). "In summary, BDNF, IGF-1 and IGFBP-3 were not affected by a history of pathological use of cocaine supported by the absence of associations with other molecules sensitive to cocaine addiction." (PMID 25734326, 2015). "Focusing on cocaine addiction, we observed no changes in the plasma concentrations of IGF-1 and IGFBP-3 of abstinent users and concentrations did not correlated with addiction-related variables such as severity cocaine symptom, abstinence or duration of cocaine use." (PMID 25734326, 2015).
congenital heart disease (1 paper, 2020). A heart disease that is present at birth. "The authors recommend that consecutive measurements of serum IGF-l and IGFBP-3 may be supportive in monitoring the effect of nutritional supplement in congenital heart disease." (PMID 33905470, 2020). "The authors reported that underweight infants with congenital heart disease had a significantly reduced energy intake and substantially low serum IGF-1 and IGFBP-3 levels." (PMID 33905470, 2020).
coronary artery stenosis (1 paper, 2025). "In NOT rule eligible patients and in those with a maximum hs-TnT >5 and <14 (n = 154), IGFBP-3 with ΔIGFBP-3 improved the prediction of 70% coronary artery stenosis over clinical variables (ΔAUC 0.03, 95% CI −0.01 to 0.06, and 0.04, 95% CI 0.002–0.10)." (PMID 40177504, 2025).
coronary atherosclerosis (1 paper, 2021). Atherosclerosis of the coronary vasculature. "Moreover, growth hormone, the stimulus for IGF production and the key regulator of IGFBP3, has been shown to be associated with coronary atherosclerosis, independently of other RFs." (PMID 35187107, 2021).
Creutzfeldt-Jakob disease (1 paper, 2023). "Also PRNP variants rs1799990, rs6107516 and rs6116492, which are associated with Creutzfeldt-Jakob disease and share some symptoms with ALS, and IGFBP3 variants rs10597497, rs2965072 and rs1542820, which are associated with brain volume and morphology changes, are potentially relevant to ALS." (PMID 37531027, 2023).
developmental delay (1 paper, 2017). "PPIA, IGFBP-3, GCK, GRB10, and H2AFV have HI <10% and that patient’s phenotype includes global developmental delay, tall stature, macrocephaly, depressed nasal bridge, pectus excavatum, and hypospadias." (PMID 28387648, 2017).
dilated cardiomyopathy (1 paper, 2025). Cardiomyopathy which is characterized by dilation and contractile dysfunction of the left and right ventricles. "The expression of IGFBP3 is augmented in HCM, dilated cardiomyopathy, and ischemic cardiomyopathy." (PMID 40271123, 2025).
ductal carcinoma in situ (1 paper, 2005). "Moreover, both the histological location of IGFBP-3 and variations in its immunoreactivity have been compared in this series of invasive ductal breast cancers with concomitant evaluation of IGFBP-3 expression in synchronous ductal carcinoma in situ (DCIS) within the same tumour specimens." (PMID 15642160, 2005).
dwarfism (1 paper, 2022). "Our objective was to analyze and compare the clinical effects of different doses of rhGH in the treatment of idiopathic dwarfism and its effects on the levels of IGF-1 and IGFBP-3." (PMID 35634620, 2022). "This will aid in more comprehensively analyzing the effect of high-dose rhGH treatment in patients with idiopathic dwarfism, as well as its impact on IGF-1 and IGFBP-3 levels." (PMID 35634620, 2022).